AHR (aryl hydrocarbon receptor)
Diseases named in the same sentence as AHR in open-access papers (continued):
Sharing a sentence is not in itself a finding about the gene and the disease.
bladder cancer (continued). "Overall, these results suggest that AhR may serve as a biomarker for poor prognosis in bladder cancer, and that 3‐IAA may modulate AhR signaling by directly binding to the receptor, thereby regulating cellular transcriptional activity and physiological responses." (PMID 40557796, 2025). "However, our results, nor information in literature, provides clues why AHR pathway activation is so specific for bladder cancer, so this will require further investigations." (PMID 35710704, 2022). "Additionally, AhR KO mice did not display BBN-induced downregulation of UGT1A or Cyp1a1, which was down-regulated by BBN-induced bladder cancer of wild-type mice." (PMID 27690298, 2017).
liver disease (20 papers, 2021 to 2026). "Further, AhR recognizes a plethora of ligands of physiologic, microbial, and xenobiotic origin and is a promising candidate for treating liver diseases associated with dysbiosis." (PMID 38886098, 2024). "Prevailing evidence has highlighted impaired intestinal barrier integrity and gut permeability as pathogenic factors in many liver diseases, which in turn has led to extensive attention on AHR signaling." (PMID 36139083, 2022). "Classically, AHR is known for regulating xenobiotic metabolic genes; it is also recognized as a key regulator of immune regulation, cell proliferation, and differentiation that underlies a broad spectrum of liver diseases." (PMID 41516226, 2025). "Previous studies have indicated that microbiota-regulated AHR signalling exhibits considerable complexity across different liver diseases, and further research is needed to elucidate the mechanisms underlying these diverse effects." (PMID 41277458, 2025). "By analyzing current controversies and cognitive gaps in the field, this article seeks to provide a framework for clarifying the complex role of AhR in liver diseases and to guide future exploration of targeted intervention strategies." (PMID 41585883, 2025). "AHR signalling is a critical regulator of intestinal and hepatic immune responses, playing an important role in intestinal homoeostasis and liver diseases." (PMID 41277458, 2025). "Administration of ILA has been shown to be beneficial for anti‐inflammatory and eubiotic maintenance in liver disease via AhR‐mediated activation of intestinal immune cells." (PMID 39854052, 2025). "The kynurenine pathway represents a potential target for modulating gut microbiota in liver inflammatory diseases and plays a crucial role in the inflammatory signaling of the AhR–liver axis." (PMID 39940736, 2025). "Indole mitigates inflammation and alleviates the progression of liver diseases through its anti-inflammatory properties and interaction with the aryl hydrocarbon receptor (AhR) pathway." (PMID 41437983, 2025). "We anticipate that this work will establish a logical framework to support future research in more rationally exploring novel AhR-targeted intervention strategies for liver diseases." (PMID 41585883, 2025). "Liver diseases such as alcoholic steatohepatitis, fibrosis, and cirrhosis are marked with diminished AhR expression." (PMID 38886098, 2024). "In recent decades, the metabolites of Trp produced by the microbiota or host cells from the diet are novel AHR agonists that have been shown to be involved in various diseases, especially liver disease." (PMID 36139083, 2022). "The focus on AHR signaling will identify a promising target in the gut microbiota for better understanding and therapeutic opportunities in liver diseases." (PMID 36139083, 2022). "Our unpublished data shows CCl4, which is not a ligand for AhR and induces hepatic inflammation, also influences the accumulation of immune cells in the inflamed liver and decreases the hepatic disease severity after the knockout AhR in Tregs." (PMID 36601108, 2022). "Recent studies have raised interest in the relationship between the AHR pathway and liver diseases, including alcoholic liver disease (ALD), nonalcoholic fatty liver disease (NAFLD), and liver failure." (PMID 36139083, 2022). "Generally, AHR signaling is one of the critical points in the gut-liver axis, showing therapeutic potential in liver diseases." (PMID 36139083, 2022). "In brief, these publications show that AHR is an effective and promising target for gut microbiota intervention for the treatment of liver diseases." (PMID 36139083, 2022). "In this review, we summarize recent progress and examine the role of AHR signaling as a target for gut microbiota intervention in liver diseases." (PMID 36139083, 2022).
liver disease (continued). "A growing number of studies on liver diseases have focused on microbial ecology interventions to regulate AHR signaling, including antibiotics, prebiotics/probiotics and faecal microbiota transplantation (FMT)." (PMID 36139083, 2022). "Considering the strong link between the gut microbiota and AHR signaling, it is feasible to explore gut microbiota modulation of the AHR pathway as a potential therapeutic target for liver diseases." (PMID 36139083, 2022). "The manifold functions of AHR in regulating inflammatory, fibrogenic, or tumorigenic processes in the liver suggest AHR as a promising therapeutic target in various liver diseases." (PMID 34075438, 2021). "In this review, we summarize the current knowledge about the role of AHR in hepatic immune responses in the healthy liver as well as in inflammatory liver disease." (PMID 34075438, 2021). "Indole metabolites produced by intestinal bacteria are known to control liver disease manifestation through a variety of mechanisms in addition to AhR activation and IL-22 production." (PMID 34209524, 2021). "Therefore, in order to develop AHR-based therapeutic strategies for liver disorders, a thorough understanding of AHR function in the respective disease-driving pathways is required." (PMID 34075438, 2021). "Therefore, future studies in humanized mice and patients are needed to further explore AHR-based therapies in liver disease." (PMID 34075438, 2021). "However, current research on the specific regulatory mechanisms of AhR in hepatocyte autophagy remains insufficient, and future studies are urgently needed to explore its role in maintaining liver homeostasis and the development of liver diseases." (PMID 41585883, 2025). "Moreover, we discuss the potential of AHR as a new therapeutic target in liver disease." (PMID 34075438, 2021). "Recent studies have demonstrated that AHR exerts a multifaceted regulatory role in liver diseases by integrating metabolic and immune signaling pathways; however, the specific role of AHR in MAFLD is not clear." (PMID 41516226, 2025). "Multiple AHR-targeted cells, including hepatocytes, hepatic stellate cells (HSCs), macrophages, natural killer T (NKT) cells and CD4+ T cells, are critical or potential players in different liver diseases." (PMID 36139083, 2022).
allergic asthma (19 papers, 2012 to 2025). A asthma with a basis in a pathological type I hypersensitivity reaction. "This latter finding is consistent with previous publications showing that AhR-deficient mice developed allergic asthma in preclinical OVA and cockroach allergen models." (PMID 34744763, 2021). "However, despite these differences, our results further reaffirm the importance of the AhR in suppressing inflammation associated with the allergic asthma phenotype." (PMID 34744763, 2021). "Because DC plays an essential role in the pathogenesis of allergic asthma, we then asked whether IP modulated DC’s function through AhR by the use of C57BL/6 mice carrying a high-responder allele (AhRb-1) and a congenic strain carrying a low-responder allele of AhR (AhRd)." (PMID 29581487, 2018). "Our previous study demonstrated that activation of AhR leads to epithelium-derived alarmins release in airway epithelial cells of severe allergic asthma." (PMID 39707175, 2024). "Our previous study demonstrated that DEP induces alarmins release in airway epithelial cells of severe allergic asthma via AhR activation." (PMID 39707175, 2024). "The relevance of the aryl hydrocarbon receptor (AhR), a ligand-dependent transcription factor, has been investigated in several inflammatory diseases, including allergic asthma." (PMID 38915403, 2024). "AhR, the receptor for both EDCs and flavonoids, is expressed in all major inflammatory cells in allergic asthma, including eosinophils, T cells, B cells, and epithelial cells." (PMID 37315181, 2023). "First, the expressions of aryl hydrocarbon receptor known as a receptor of phthalate and flavonoid were measured by western blot in lung tissue of our MnBP‐treated allergic asthma model." (PMID 37315181, 2023). "In addition, RNA-seq analysis suggests that autophagy is one of the major pathways and that CALCOCO2/NDP52 and S1009 are major autophagy-associated genes in AT2 cells that may contribute to the AhR-mediated cockroach allergen–induced airway inflammation and, subsequently, allergic asthma." (PMID 35935956, 2022). "AhR as a receptor for environmental contaminants has been shown to protect against allergic airway information and remodeling in allergic asthma by using global AhR knockout mice." (PMID 35935956, 2022). "Yet, our data herein confirm that AhR expression also protects against the development of allergic asthma." (PMID 34744763, 2021). "Our studies reveal a previously unidentified functional axis of AhR–RhoA in regulating TGFβ1 expression and signaling activation, representing a potential therapeutic target for allergic asthma." (PMID 33936062, 2021). "Blockage of the AhR–RhoA axis represents a promising novel therapeutic approach for the treatment of allergic asthma." (PMID 33936062, 2021). "These confirmatory data strongly support the general regulation of the allergic asthma phenotype by the AhR." (PMID 34744763, 2021). "In addition, apigenin administration effectively reduced the expression of aryl hydrocarbon receptor in MnBP‐treated allergic asthma mice." (PMID 37315181, 2023). "Recently, it has been shown that the aryl hydrocarbon receptor (AhR) may be involved in suppressing the development of allergic asthma." (PMID 34744763, 2021). "Moreover, severe asthmatic patients that exhibit high AhR nuclear translocation, have the highest levels of these type 2-inducing cytokines, indicating a link between AhR and severe allergic asthma." (PMID 33233810, 2020). "Since AHR is a key clinical feature of allergic asthma, we investigated the effect of TSLP receptor deletion on both basal and HDM-induced AHR by evaluating lung function parameters." (PMID 41259396, 2025). "Consistent with a role for ILC2, influenza infection-induced AHR occurred independently of the adaptive immune response, but depended on the IL-33-ST2 signalling pathway, similar to allergic asthma." (PMID 23562755, 2013).
allergic asthma (continued). "Single-cell transcriptomics from allergen-challenged bronchoalveolar brushings of allergic asthma and non-asthmatic allergic control subjects were analyzed for ROS, senescence, and AhR activity." (PMID 41596081, 2025). "AhR specific agonists TCDD, Curcumin and FICZ have been shown to suppress allergic immune responses in several mice models, providing evidence for the involvement of AhR ligands in the pathogenesis of allergic asthma." (PMID 24905409, 2014). "In our study, farrerol can inhibit NF-κB activation induced by OVA in an allergic asthma model, but not in acute lung injury model, which suggests that the decreased NF-κB activation could account for the inhibition of airway inflammation and AHR." (PMID 22563373, 2012).
chronic obstructive pulmonary disease (19 papers, 2004 to 2025). A chronic and progressive lung disorder characterized by the loss of elasticity of the bronchial tree and the air sacs, destruction of the air sacs wall, thickening of the bronchial wall, and mucous accumulation in the bronchial tree. "AHR deficiency enhanced airway inflammation and remodeling in a murine chronic asthma model, and also caused the development of chronic obstructive pulmonary disease, indicating its importance as a central player in maintaining normal lung function and determining disease severity." (PMID 35145399, 2021). "AhR has a ligand-specific impact on the lungs and can either aggravate or ameliorate chronic obstructive pulmonary disease." (PMID 35743162, 2022). "As chronic obstructive pulmonary disease (COPD) is associated with smoking habits, AHR activation by tobacco smoke dioxins may be potentially involved in the pathogenesis of COPD." (PMID 33445793, 2021). "We also affirmed low AHR but high LRIG1 levels in lung tissues of chronic obstructive pulmonary disease (COPD) patients." (PMID 34576152, 2021). "In chronic lung diseases such as chronic obstructive pulmonary disease (COPD) and asthma, AHR activation worsens respiratory function through enhanced mucus production and airway remodelling." (PMID 40949107, 2025). "Lung fibroblasts gained from patients suffering from chronic obstructive pulmonary disease (COPD) express less AhR protein than patients without COPD and show decreased upregulation of NQO1 and Srxn in response to cigarette smoke extract." (PMID 27829840, 2016).
lung diseases (18 papers, 2012 to 2025). "Additional studies are needed to elucidate the functional significance of increased miR-96 associated with AhR deficiency, and the potential role of this miRNA towards pulmonary disease development." (PMID 28079158, 2017). "Dominant pathways associated with these epigenetic changes include those linked to G-protein coupled receptor signaling, aryl hydrocarbon receptor signaling and xenobiotic metabolism signaling, all of which have been associated with cigarette smoking and lung disease." (PMID 28273093, 2017). "Benzopyrene and dioxin-like compounds are released during smoking and are metabolized by AhR, thus releasing further carcinogenic metabolites, which may contribute to tobacco-associated inflammation and lung disease." (PMID 28453567, 2017). "Therefore, the AhR action may still promote further toxic events linked with lung disease, including cancer." (PMID 35203356, 2022). "Further investigation may yield a novel treatment strategy for AhR-associated lung diseases." (PMID 22500183, 2012). "Although many studies have investigated the role of AhR in the context of smoke-induced lung diseases, only a few studies have reported the role of AhR in the brain exposed to particulate matter, including wildfire smoke or wood smoke." (PMID 39408618, 2024). "Our goal is to provide insight into the high translational potential of the AHR in the meaningful management of infants and adults with these lung disorders that lack curative therapies." (PMID 35163440, 2022). "Deciphering these knowledge gaps would advance AHR biology and lay the foundation for selecting and developing the most effective AHR ligands as novel therapies for lung disorders, including ALI, COPD, and BPD." (PMID 35163440, 2022). "Nevertheless, there are observations strongly indicating that AhR signaling can be beneficial in lung diseases mediated by inflammation and oxidative damage." (PMID 35743162, 2022). "These contrasting findings further emphasize the complexity of AHR biology in lung diseases, wherein the outcome is both ligand and context-dependent." (PMID 35163440, 2022). "CYP1A1 metabolizes multiple exogenous and endogenous substrates, which is mainly controlled by the aryl hydrocarbon receptor (AHR) and has been found to be involved in lung disease including COPD by regulating inflammation and oxidative stress." (PMID 36578523, 2022). "Hence, identifying novel non-toxic AHR ligands, such as OM, is important for developing the AHR as a clinically relevant therapeutic target in oxidant injury- and inflammation-mediated lung disorders." (PMID 35163440, 2022). "Furthermore, OM activates AHR and attenuates hyperoxic injury in adult mice in vivo and adult human lung H441 cells in vitro, which indicates that OM can be used as an AHR agonist to understand AHR biology in hyperoxia-mediated lung disorders." (PMID 35163440, 2022). "However, this acute exposure model allowed us to interrogate mechanistically how the AhR suppresses smoke-induced neutrophilia, an immune cell type that is part of an inflammatory response whose dysregulation in susceptible smokers may contribute to lung disease." (PMID 33659010, 2021). "Continued investigation into the mechanistic basis by which the AhR controls inflammation may uncover new therapeutic targets to combat prevalent lungs diseases in both current and former smokers around the world." (PMID 35295140, 2021). "Domain databases also determined shared protein domain with AHR (aryl hydrocarbon receptor) and ARNT (aryl hydrocarbon receptor nuclear translocator), involved in regulation of inflammatory processes implicated in multi-factorial diseases like pulmonary disorders." (PMID 26731791, 2016). "The infection of macrophages by Mycobacterium tuberculosis triggers AhR signaling through the regulation of IL23A transcription, offering potential avenues for the treatment of pulmonary disease due to the high expression of AhR in the lungs." (PMID 38680494, 2024).
lung diseases (continued). "AHR and LRIG1 have been reported to be expressed ubiquitously in all tissues; and they are dominantly expressed in lung epithelium, suggesting that the expression pattern of AHR and LRIG1 plays an important role during the pathogenesis of lung diseases." (PMID 34576152, 2021). "Thus, typical AhR xenobiotic ligands such as TCDD and BaP may contribute to the development of lung diseases." (PMID 35743162, 2022).